METTL3 (methyltransferase 3, N6-adenosine-methyltransferase complex catalytic subunit)
Diseases named in the same sentence as METTL3 in open-access papers (continued):
Sharing a sentence is not in itself a finding about the gene and the disease.
melanoma (continued). "Similar observations have been made in melanoma and lung cancer, where high expression of METTL3 in macrophages is beneficial for immunotherapy." (PMID 39372415, 2024). "Activation of multiple dsRNA sensors (PKR, MDA5, OAS-RNase L, and RIG-I) contributed to enhanced anti-tumor immunity upon inhibition of METTL3 in a mouse melanoma model." (PMID 39221819, 2024). "In melanoma, METTL3 activity augments the expressionof matrixmetallopeptidase 2 (MMP2), thereby increasing the motility of humanmelanoma cells and facilitating migration and invasion." (PMID 36692498, 2023). "Further research suggested METTL3 accelerated invasion and migration of melanoma cells by upregulating matrix metallopeptidase 2 (MMP2)." (PMID 37124930, 2023). "In malignant melanoma, METTL3 activates the RAF/MEK/ERK pathway by upregulating EGFR, inducing resistance to PLX4032, a BFAF (V600E) kinase inhibitor." (PMID 37264402, 2023). "In the group of 35 human primary melanomas and 35 metastasis melanomas it was proven that METTL3 promotes the invasion and migration of melanoma cells." (PMID 36982460, 2023). "In melanoma, METTL3-mediated stabilization of the uridine cytidine kinase 2 (UCK2) by m6A modification plays a role in melanoma metastasis by enhancing the Wnt/β-catenin pathway." (PMID 37369946, 2023). "Depletion of Mettl3 and Mettl14 significantly upregulated PD-L1, and Mettl3 or Mettl14 deficient enhanced the response to anti-PD-1 treatment in pMMR-MSI-L CRC and melanoma." (PMID 36960074, 2023). "For example, Yin’s group has reported that deletion of METTL3 in myeloid cells attenuated the effect of PD-1 blockade in B16 melanoma, and METTL3 KO mice showed increased infiltration of M1/M2-like TAMs and Treg cells in tumor sites compared to control mice." (PMID 36960074, 2023). "Studies have shown that the expression of METTL3 is upregulated in human melanoma cell lines, and it promotes melanoma cell proliferation." (PMID 37124930, 2023). "Since c-Met is upstream of the Akt pathway, METTL3 knockdown also decreases total Akt levels, indicating that the METTL3/c-Met/Akt axis is important for melanoma cell survival and migration." (PMID 36008936, 2022). "In conjunctival melanoma, METTL3‐mediated m6A methylation can regulate the cell proliferation, cell cycle, invasion and metastasis of melanoma cells by affecting C‐Met." (PMID 36324258, 2022). "For example, in melanoma, all of METTL3/14, ALKBH5 and FTO can modulate tumor response to anti-PD-1 therapy in mice." (PMID 35590394, 2022). "In mismatch-repair-proficient or microsatellite instability-low (pMMR-MSI-L) CRC and melanoma mouse models, depletion of METTL3 enhances the tumor response to anti-PD-1 treatment through stabilizing the Stat1 and Irf1 mRNA via YTHDF2." (PMID 36008936, 2022). "Studies have shown that melanoma cell lines express higher levels of METTL3 than normal melanocytes, resulting in increased m6A methylation on total RNA." (PMID 36008936, 2022). "Here, we demonstrated that m6A level was highly elevated in acral melanoma tissues, along with the expression of METTL3, one of the most important m6A methyltransferase." (PMID 35117988, 2021). "In melanoma cell lines, METTL3 was significantly highly expressed at both the mRNA and protein level compared to that in normal human epidermal melanocytes (HEMa)." (PMID 35117988, 2021). "In consistence with their studies, we also identified the critical role of METTL3 in melanoma cell growth, migration, and invasion." (PMID 35117988, 2021). "In our study, METTL3 was found to promote melanoma development by enhancing cell growth and invasion in vivo and in vitro." (PMID 35117988, 2021). "Taken together, METTL3 exhibited cancer-promoting effects based on transcriptional regulation in melanoma." (PMID 35117988, 2021).
melanoma (continued). "For A375 and A875 cells, the colony forming rates of NTC cells were 3.9- and 2.7-fold higher, respectively, than those of shMETTL3 cells, which meant that METTL3 knockdown inhibited melanoma cell proliferation and colony formation ability in vitro." (PMID 35117988, 2021). "Though the results need to be confirmed by in vivo studies, they suggest a potential therapeutic benefit of METTL3 inhibitors in melanoma." (PMID 34105069, 2021). "Though many cancers show deregulated expression of m6A and METTL3, the role of each in melanoma still remains to be fully elucidated." (PMID 34105069, 2021). "For example, M6A methyltransferase METTL3 is upregulated in melanoma and modulates melanoma cell invasiveness through MMP2." (PMID 34026852, 2021). "Cell counting, CCK-8 assays were carried out and indicated that the knockdown of METTL3 expression significantly inhibited melanoma cell proliferation." (PMID 35117988, 2021). "In accordance with this, elevated METTL3 expression was detected in human melanoma cell lines, which led to increased m6A activity, colony formation, and invasion of melanoma cells through MMP2 and N-cadherin accumulation." (PMID 35117988, 2021). "Wound healing assays and Transwell analysis indicated that METTL3 knockdown significantly impaired the abilities of migration and invasion in melanoma cells." (PMID 35117988, 2021). "Immunohistochemistry (IHC) also determined the upregulated protein expression of METTL3 in 12/12 (100%) melanoma tissue samples relative to the corresponding adjacent normal tissues." (PMID 35117988, 2021). "In METTL3 knockdown xenograft mouse models, we observed decreased volumes and weights of melanoma tissues." (PMID 35117988, 2021). "To further confirm the relationship between METTL3 expression and the effector functions of NK cells, we used a mouse model of pulmonary metastases of B16/F10 melanoma." (PMID 34535671, 2021). "METTL3 promotes cell invasion and migration and increases MMP2 and N‐cadherin levels in melanoma cells, which are completely reversed in cells transfected with inactivated METTL3 through site mutant." (PMID 33029866, 2020). "In melanoma, upregulation of METTL3 expression was found to play a role in the invasion and migration of human melanoma cells by promoting the expression of matrix metallopeptidase 2 (MMP2)." (PMID 32398132, 2020). "Melanoma cells with METTL3 knockdown also displayed significantly greater migratory ability and slightly accelerated cell growth." (PMID 31722709, 2019). "Finally, the efficacy of METTL3 inhibition was also tested on human melanoma model (A375) and human T cells." (PMID 39568154, 2024). "One such study revealed that METTL3 promotes the growth and mobility of melanoma cells." (PMID 39247584, 2024). "Based on this discovery, we designed specific RNA primers for RIP experiments (for details), and the results showed that METTL3 could bind to its mRNA in melanoma and eIF5A‐Hyp could also bind to the METTL3 mRNA." (PMID 38952061, 2024). "Here, we aimed to uncover the pro‐oncogenic mechanism of DHPS in melanoma by mediating the hypusination of eIF5A to promote the m6A modification of METTL3 itself through a multi‐omics approach to elucidate the value of DHPS as a therapeutic target for melanoma." (PMID 38952061, 2024). "The m6A methyltransferase METTL3 is upregulated in human melanoma tissue, which activates matrix metalloproteinase (MMP) 2, promotes the expression of c-met and p-Akt proteins, leads to the formation of melanoma cell colonies, and causes melanoma cell invasion." (PMID 39247584, 2024). "This evidence suggests that AR extracts may reduce the m6A modification level of RNA in melanoma by lowering the level of METTL3." (PMID 39247584, 2024). "This suggests that TXNDC5 may be the downstream target of METTL3-m6A in melanoma and may play an important role in melanoma carcinogenesis." (PMID 38666927, 2024).
melanoma (continued). "Similarly, the deletion of METTL3 or METTL14 in immune-resistant melanoma tumor cells makes the tumor sensitive to immunotherapy." (PMID 39372415, 2024). "The study found a new target, the miR-302a-3p/METTL3 axis, for future melanoma therapies." (PMID 36982460, 2023). "METTL3 could modulate the mRNA level of uridine cytidine kinase 2 (UCK2) through m6A modification to enhance its stability in melanoma." (PMID 37124930, 2023). "miR-302a-3p was responsible for the upstream regulation of METTL3 in melanoma." (PMID 36982460, 2023). "MiR-302a-3p was investigated as an inhibitor factor of METTL3 expression in melanoma." (PMID 36982460, 2023). "Targeted treatment of METTL3 may improve the efficacy of PLX4032 in patients with advanced melanoma." (PMID 37264402, 2023). "shRNA-mediated knockdown of METTL3 attenuates melanoma cell colony formation and invasion in vitro." (PMID 36008936, 2022). "Similarly, in colorectal cancer and melanoma, METTL3 or METTL14 improved tumor cells to anti-PD-1 therapy by regulating CD8+ T cells." (PMID 35590394, 2022). "Some studies showed that the m6A RNA methyltransferase METTL3/14 could enhance response to anti–PD-1 treatment in pMMR-MSI-L melanoma and CRC." (PMID 35309906, 2022). "METTL3 was also reported to regulate the sensitivity of melanoma cells to PLX4032." (PMID 36291811, 2022). "Furthermore, the role of METTL3 in melanoma immunology is also attributed to its effect on tumor-infiltrating macrophages." (PMID 35693795, 2022). "Knockdown of METTL3 decreased global m6A level in melanoma cells." (PMID 35117988, 2021). "Importantly, we uncovered that METTL3 affects melanoma progression by targeting m6A-TXNDC5 mRNA, and it is hoped that these findings will contribute to a potential therapeutic strategy in acral melanoma." (PMID 35117988, 2021). "Taken together, TXNDC5 may be the downstream target of METTL3-m6A in melanoma and may play an important role in melanoma carcinogenesis." (PMID 35117988, 2021). "As high expression of METTL3 correlated with advanced stage of melanoma, which was revealed above, we speculated that the upregulation of METTL3 might be involved in migration and invasion of melanoma cells." (PMID 35117988, 2021). "Furthermore, METTL3 knockdown suppressed the proliferation, migration, and invasion of melanoma cells." (PMID 35117988, 2021). "Few studies have explored the functions of METTL3 inside melanoma cells." (PMID 35117988, 2021). "However, our research obtained first insight into the dysregulation of m6A modification and METTL3 in Chinese acral melanoma tissues and revealed the clinic significance of METTL3." (PMID 35117988, 2021). "To explore the function of METTL3 in melanoma, we silenced the expression of METTL3 in A375 and A875 cells with shRNA transfection, which reduced METTL3 expression by approximately 90% relative to that in non-targeted control (NTC) cells, as confirmed by qRT-PCR and Western blotting." (PMID 35117988, 2021). "Specifically, the expression of METTL3 is upregulated in PLX4032-resistant melanoma cells, increasing m6A modification on EGFR mRNA, which in turn promotes EGFR protein translation efficiency, ultimately causing melanoma cells to become resistant to PLX4032 targeted therapy." (PMID 41584846, 2025). "Moreover, myeloid‐specific METTL3 depletion attenuates efficacy of anti‐PD‐1 in melanoma." (PMID 38545841, 2024). "METTL3 may be involved in the proliferation, invasion, migration and resistance of melanoma cells." (PMID 35945641, 2022). "Importantly, Mettl3 depletion in macrophages impairs PD-1 blockade therapeutic efficacy in B16 melanoma, suggesting that METTL3 in macrophages may synergize with PD-1-based therapy." (PMID 34315512, 2021). "Results showed that the mRNA expression of METTL3, the core m6A methyltransferase, was significantly upregulated (p < 0.0001), which may be responsible for the upregulation of global m6A levels in melanoma." (PMID 35117988, 2021).
melanoma (continued). "Depletion of the methyltransferase METTL3 and METTL14 to suppress m6A mRNA modification enhanced the response of pMMR-MSI-L CRC and melanoma to anti-PD-1 therapy." (PMID 41194259, 2025). "Therefore, depletion of Mettl3 in myeloid cells contributes to the formation of an immunosuppressive microenvironment, including increased infiltration of M1/M2-like TAMs and regulatory T cells, and promotes the growth and metastasis of Lewis lung carcinoma and melanoma in mice." (PMID 38322265, 2024). "Compelling evidence indicates that METTL3 is negatively correlated with the efficacy of anti-PD-1 therapy in various tumor cells, including CRC, melanoma, and NSCLC." (PMID 38322265, 2024). "To assess the therapeutic potential of METTL3 inhibition in ICB therapy, we administered a PD‐1 monoclonal antibody (anti‐PD‐1) and STM2457 to immunocompetent C57BL/6 mice bearing B16 melanoma cells." (PMID 39568154, 2024). "We then utilised mouse melanoma (B16) and mouse colorectal adenocarcinoma (MC38) models to investigate the effects of METTL3 inhibition on immunotherapy, and analysed the dynamics of the tumour microenvironment via single‐cell RNA‐seq (scRNA‐seq)." (PMID 39568154, 2024). "For example, depletion of Mettl3/14 strengthens the response to anti‐PD‐1 therapy by promoting interferon-gamma (IFN‐γ)‐Stat1‐Irf1 signaling in CRC and melanoma." (PMID 36960074, 2023). "Several m6A regulators including METTL3, YTHDF1, HNRNPA2B1, FTO, and IGF2BP3 are involved in melanoma." (PMID 37124930, 2023). "A study found that METTL3 induced UCK2 m6A hypermethylation and promoted the metastasis of melanoma cells through the WNT/β-catenin pathway." (PMID 35945641, 2022). "We then investigated the expression of common methyltransferases and demethylases like METTL3, METTL14, FTO and ALKBH5 in three melanoma cell lines, which demonstrated that the process of m6A modification was available in melanoma cell lines." (PMID 36324258, 2022). "For instance, the ‘writers’ METTL3 is upregulated and governs in invasion/migration through MMP2 in melanoma." (PMID 34446007, 2021). "Inhibition of m6A mRNA modification by depletion of methyltransferases, Mettl3 and Mettl14, enhanced response to anti-PD-1 treatment in pMMR-MSI-L CRC and melanoma." (PMID 34526985, 2021). "According to The Cancer Genome Atlas (TCGA) melanoma dataset, intratumoral TXNDC5 expression was positively correlated with METTL3 expression." (PMID 35117988, 2021). "Intriguingly, both “writers” inhibition (METTL3 or METTL14) and “erasers” inhibition (FTO or ALKBH5) are proved to enhance the efficacy of anti-PD-1 blockade even in the same cancer (melanoma)." (PMID 34526985, 2021). "The PI3K/AKT/mTOR pathway has been implicated in the development of various types of cancer regulated by m6A proteins, including METTL3/WTAP in AML, METTL3 in RCC/PDAC, ALKBH5 in EOC, and FTO in melanoma and EC." (PMID 32513173, 2020). "To determine the role of m6A in melanoma cell function, we performed gain-of-function tests of the m6A writers METTL3 (Methyltransferase Like 3) and METTL14 (Methyltransferase Like 14)." (PMID 31239444, 2019). "Collectively, these data support the notion that targeting METTL3 in conjunction with ICIs may provide therapeutic benefits across multiple cancer types, including CRC, TNBC, NAFLD-HCC, and melanoma." (PMID 39987091, 2025). "In melanoma, this context-specific regulation may explain why WTAP displays tumor-suppressive properties, in contrast to the oncogenic roles of METTL3 and METTL14." (PMID 41301778, 2025). "Consequently, targeting these pathways, such as inhibiting the writer METTL3, erasers FTO/ALKBH5, or knocking down YTHDF3, represents a prospective therapeutic approach for melanoma progression and overcoming chemoresistance." (PMID 41157107, 2025).
melanoma (continued). "Additionally, western blot analysis revealed that the expression of three vital proteins that regulate m6A modification, namely METTL3, YTHDF2, and YTHDC1, was reduced in melanoma cells after DHPS knockdown." (PMID 38952061, 2024). "Moreover, depletion of Mettl3 and Mettl14 enhanced the response to anti-PD-1 treatment in pMMR-MSI-L CRC and melanoma." (PMID 34526985, 2021). "METTL3 overexpression promoted the accumulation of MMP2 and N-cadherin in melanoma cells." (PMID 31921660, 2019). "Furthermore, knockdown of METTL3 and METTL14 prevented the effect of FTO knockdown on cell growth/proliferation, migration, invasion, and cell viability in melanoma cells in suspension." (PMID 31239444, 2019). "To determine whether regulation of these melanoma-promoting genes by FTO is m6A-dependent, we assessed the role of m6A by knocking down the m6A methyltransferases METTL3 and METTL14." (PMID 31239444, 2019). "Conditional ablation of METTL3 in CD4+CD8+ double-positive thymocytes disrupts m6A-dependent CREB1 translation and phosphorylation, impairing iNKT cell proliferation, lineage differentiation, and cytokine production, ultimately compromising antitumour immunity against melanoma." (PMID 41424859, 2026). "The Co‐IP assays revealed that DHPS could not directly bind to METTL3 in melanoma cells, while eIF5A‐Hyp could bind to METTL3." (PMID 38952061, 2024). "For example, knocking out METTL3 in melanoma can inhibit tumor development and increase the infiltration of CD8+ T cells, but another study has shown that the absence of METTL3 expression in macrophages can promote the growth and metastasis of melanoma and weaken the efficacy of PD-1 blockade." (PMID 39372415, 2024). "The inhibition of METTL3 and METTL14 via methyltransferase inhibitors suppressed N-methyladenosine (mA) mRNA modification and enhanced the response to anti-PD-1 therapy in pMMR-MSI-L CRC and melanoma, highlighting the relevance of RNA methylation in adaptive immunity." (PMID 34230220, 2021). "Ultimately, however, they suggest that the regulation of these melanoma-promoting genes by FTO and other proteins might critically affect gene expression in melanoma (e.g., the methyltransferases METTL3 and METTL14) and further studies on the therapeutic potential of such are warranted." (PMID 34105069, 2021). "Comparing primary melanoma and metastases, we found that ALKBH5, ELAVL1, FMR1, HNRNPA2B1, HNRNPC, IGF2BP1/2/3, KIAA1429, LRPPRC, RBM15, YTHDC1/2, YTHDF1/3, and ZC3H13 were significantly upregulated in metastases, while RBM15B and METTL3 were significantly upregulated in primary melanoma." (PMID 34993195, 2021). "Subsequent studies revealed that METTL3 could not regulate the expression of YTHDC1/YTHDF2 proteins in melanoma, which also predicts that the methylation modifications regulated by METTL3 are not required for all genes, but that METTL3‐mediated m6A‐methylation modification is dependent on DHPS." (PMID 38952061, 2024). "Overexpression of m6A catalytic site mutant in METTL3 did not produce a similar increase in MMP2, suggesting that m6A activity of METTL3 is important for melanoma cell invasiveness." (PMID 34105069, 2021).